PMP22 (peripheral myelin protein 22)
Diseases named in the same sentence as PMP22 in open-access papers (continued):
Sharing a sentence is not in itself a finding about the gene and the disease.
hereditary peripheral neuropathy (4 papers, 2019 to 2025). An instance of peripheral neuropathy that is caused by an inherited genomic modification in an individual. "Charcot-Marie-Tooth disease type 1 A (CMT1A) is the major subtype of hereditary peripheral neuropathies and arises from a 1.5 megabase (Mb) tandem duplication in chromosome 17p11.2-p12 that contains the complete peripheral myelin protein 22 (PMP22) gene." (PMID 40864398, 2025). "PMP22, and in a lesser proportion MPZ, involvement is not enough to explain hearing loss in patients suffering from hereditary peripheral neuropathy." (PMID 31393079, 2019).
neurodegenerative disease (4 papers, 2022 to 2025). A disorder of the central nervous system characterized by gradual and progressive loss of neural tissue and neurologic function. "For example, PMP22 mutations can induce neurodegenerative diseases, and abnormal expression of EMP3 can affect the occurrence of brain, breast, and T cell tumors." (PMID 36217151, 2022).
disease of the peripheral nervous system (3 papers, 2017 to 2025). "Although CMT is described as a disease of the peripheral nervous system, CNS involvement is reported in the literature in several CMT patients by variations in the MFN2, PMP22, GJB1, GDAP, MORC-2, NDRG1 and NEFL genes." (PMID 37238449, 2023).
neurological diseases (3 papers, 2011 to 2022). "PMP22, a member of the GAS3 family of tetraspan proteins, is associated with a variety of neurological diseases." (PMID 21518455, 2011).
PMP22 also shares sentences with these, for which no sentence is quoted: Alzheimer disease (4 papers); Huntington disease (4); autosomal dominant disease (3); chronic inflammatory demyelinating polyradiculoneuropathy (3); depression (3); DiGeorge syndrome (3); Parkinson disease (3); autism (2); cerebellar ataxia (2); developmental delay (2); diabetic neuropathy (2); entrapment neuropathies (2); epilepsy (2); glioblastoma (2); Leber hereditary optic neuropathy (2); Pes cavus (2); Williams-Beuren Syndrome (2); achondroplasia (1); amyotrophic lateral sclerosis (1); anemia (1); arterial hypertension (1); ATTRv amyloidosis (1); Azoospermia (1); brain injury (1); cardiac arrhythmia (1); congenital hypomyelinating neuropathy (1); congenital myasthenia (1); cytochrome c oxidase deficiency (1); distal hereditary motor neuronopathy type VIIB (1); distal hereditary motor neuropathy (1).
A further 55 diseases each share a sentence with PMP22 in 1 paper.